CDC6 (cell division cycle 6)
Diseases named in the same sentence as CDC6 in open-access papers (continued):
Sharing a sentence is not in itself a finding about the gene and the disease.
prostate carcinoma (21 papers, 2007 to 2025). A carcinoma that arises from epithelial cells of the prostate gland. "In this cohort, increased CDC6 expression predicted metastasis (p = 7.41e-04), and was also prominently associated with prostate cancer-specific mortality (p = 1.09e-02)." (PMID 28415728, 2017). "We therefore evaluated the correlation between elevated CDC6 expression and metastasis in a cohort of high-risk prostate cancer patients." (PMID 28415728, 2017). "CDC6 was considered as the replication licensing factor, which was also associated with epithelial-mesenchymal transition inducing androgen receptor blockade therapeutic resistance in prostate cancer." (PMID 39376555, 2024). "CDC6 expression is upregulated in prostate cancer and its overexpression confers resistance to enzalutamide and the Chk1/2 inhibitor (AZD7762)." (PMID 36997866, 2023). "It has shown that CDC6 is overexpressed in several cancers such as lung, breast, ovarian and prostate cancers as well as chronic myelogenous leukemia." (PMID 37833632, 2023). "CDC6, one of the Core genes, plays a critical role in regulation of the eukaryotic DNA replication onset, and its downregulation has been demonstrated in prostate cancer." (PMID 34249670, 2021). "Changes in CDC6 gene expression have been reported in many species of cancers, such as gastric cancer, pancreatic cancer, prostate cancer and so on, related to cancer cell proliferation, metastasis, invasiveness and drug resistance." (PMID 34136398, 2021). "It has been reported that the changes in CDC6 gene expression in many species of cancers, such as gastric cancer, pancreatic cancer, prostate cancer, are related to the proliferation, metastasis, invasiveness and drug resistance of cancer cells." (PMID 34136398, 2021). "Previous studies reported the important roles of CDC6 in different malignancies, such as hepatocellular carcinoma and prostate cancer." (PMID 32792963, 2020). "The deregulation of CDC6 expression had been reported to be involved in many cancers, such as para-small cell lung carcinomas 16, mantle cell lymphomas 17, prostate cancer 18, Nasopharyngeal carcinoma 19 and breast cancer." (PMID 33173413, 2020). "RNA-seq and subsequent validation revealed that CDC6 is one of the most prominently down-regulated genes in both prostate cancer cell lines." (PMID 28415728, 2017). "CDC6, a CIZ1 partner in the formation of pre-replication complex, is down-regulated in prostate cancer, though CDC6 overexpression is considered to be oncogenic." (PMID 26861296, 2016). "CDC6 plays a critical role in the regulation of the onset of DNA replication in eukaryotic cells and Cdc6 expression is down-regulated in prostate cancer." (PMID 19458769, 2007). "CDC6 regulates the onset of prostate cancer through the PI3K/AKT pathway." (PMID 39684684, 2024). "In prostate cancer, CDC6 exerts its carcinogenic effects by enhancing PIK3-AKT signaling." (PMID 39684684, 2024). "In addition, the nonsteroidal antiandrogen drug Casodex, which is used to treat advanced prostate cancer, represses the interaction between AR and CDC6, inhibiting DNA replication." (PMID 35743017, 2022). "In addition, CDC6 as a key regulatory target for tumorgenesis was postulated in various types of cancer including prostate cancer, neuroblastoma cell, hepatocellular carcinoma." (PMID 28969025, 2017). "In prostate cancer, LiCl participates in the reduction of DNA replication and S-phase cell cycle arrest, by disrupting the interaction of E2F factor with DNA, decreasing the expression of the cell division cycle 6 (cdc6), cyclin A, cyclin E, and cdc25C, which are regulated by E2F." (PMID 36836894, 2023). "The analysis of a TCGA database revealed that the overexpression of NAT10, CDC6, and MCM7 in prostate cancers were correlated with the Gleason score and node metastasis." (PMID 35743017, 2022). "The results revealed that expression levels of NAT10 and Ki67, CDC6, and MCM7 were increased in prostate cancers." (PMID 35743017, 2022).
prostate carcinoma (continued). "CDC6 and CDC20 have been reported to play critical roles in prostate cancer progression, and can serve as indicators for patient prognosis." (PMID 32922438, 2020). "Potential correlation between CDC6 expression and prostate cancer aggressiveness has not been previously evaluated, but this protein is normally found in proliferating cells." (PMID 28415728, 2017). "Remodelin can significantly inhibit the expression levels of CDC6 in prostate cancer cells and the proliferation ability of prostate cancer cells in vitro, regardless of whether the cells were treated with androgen-removed or androgen-treated cells." (PMID 35743017, 2022). "At the same time, to explore the effects of castration on prostate cancer, VCaP cells were subjected to long-term treatment with enzalutamide at either low (2 μM) or high (20 μM) concentrations for at least four weeks, and the expression of NAT10, CDC6, and AR was measured." (PMID 35743017, 2022). "Targeting CDC6 together with Chk1/2 inhibitor could suppress TopBP1-ATR-Chk1 signaling and increase phosphorylation of ATM, a biomarker of DNA damage, synergistically increasing the treatment efficacy in prostate cancer cells." (PMID 32792963, 2020). "Moreover, the fact that AR and CDC6-mediated DNA replication play a role in prostate cancers and their interaction alters the development of CRPC raises the potential for the utility of Remodelin in targeting DNA replication as a therapeutic approach in the treatment of prostate cancers." (PMID 35743017, 2022).
lung carcinoma (19 papers, 2011 to 2025). "Another study indicated that CDC6 was involved in the replication licensing and the proliferation, migration, and invasion of lung cancer cells mediated by miR-26a and miR-26b, and CDC6 represented potential cancer diagnostic and prognostic markers as well as anticancer targets." (PMID 38696317, 2024). "Importantly, CDC6 is upregulated in lung cancer and its higher expression is associated with a worse outcome for lung cancer patients." (PMID 36257938, 2022). "Immunohistochemical (IHC) analysis further confirmed elevated CDC6 expression in human lung cancer tissues." (PMID 41339304, 2025). "CDC6 is negatively regulated by miR26a and miR26b, decreasing proliferation and metastasis of lung cancer cells." (PMID 36101460, 2022). "Like IGF2BP2, CDC6 is also overexpressed in lung cancer tissues with poor patient survival, and CDC6 knockdown has oncogenic inhibitory activity." (PMID 36257938, 2022). "The upregulation of CDC6 was further verified in our collection of paired lung cancer tissues (n = 35), using qPCR assay." (PMID 36257938, 2022). "Mechanistically, the LCAT1/IGF2BP2 complex stabilized CDC6 mRNA via the m6A modification to increase the translation of CDC6, which then promoted the growth and survival of lung cancer cells." (PMID 36257938, 2022). "Taken together, CDC6 appears to be a direct target downstream of the LCAT1/IGF2BP2 complex for positive regulation with oncogenic potential in lung cancer cells." (PMID 36257938, 2022). "CDC6 then acts as an oncogenic protein to promote the proliferation, survival, and migration of lung cancer cells." (PMID 36257938, 2022). "Although cdc6 was more frequently observed in patients with lung cancer, the sensitivity is much lower than our expectation, which will limit its clinical use." (PMID 32249466, 2020). "The aim of this study is to investigate the possibility of cdc6 as a biomarker for circulating tumor cells in patients with lung cancer." (PMID 32249466, 2020). "In this study, we examined cdc6 expression in PBMCs from health subjects and patients with lung cancer." (PMID 32249466, 2020). "The function of CDC6 is complex, and the specific mechanisms by which it affects radiosensitivity in lung cancer needs further study." (PMID 33316778, 2020). "miR-26a/b inhibits directly migration, invasion, and proliferation of lung cancer cells by targeting CDC6." (PMID 31992202, 2020). "Our results demonstrated a distinct expression profile of cdc6 between these two groups, indicating a potential value of cdc6 as a circulating tumor cell biomarker for patients with lung cancer." (PMID 32249466, 2020). "We found 20% of patients with lung cancer were cdc6 positive in PBMCs, whereas only 4.26% was found positive in the control group (P = .039, P < .05)." (PMID 32249466, 2020). "Hypermethylation of genes such as COX7A1, TNFRSF1B, and BDNF, as well as hypomethylation of genes such as CDC6 and KRT8, may be associated with lung cancer compared to benign nodules." (PMID 39036344, 2024). "We then measured the levels of CDC6 in lung cancer cells with either IGF2BP2 or LCAT1 knockdown." (PMID 36257938, 2022). "CDC6 is highly expressed in various human cancers, including lung cancer." (PMID 36257938, 2022). "In terms of CDC6, several studies revealed its correlation with prognosis in lung cancer." (PMID 36428585, 2022). "Consistently, EdU assays showed that CDC6 depletion inhibited DNA replication in lung cancer cells." (PMID 36257938, 2022). "Next, we determined the biological consequence of CDC6 knockdown in lung cancer cells." (PMID 36257938, 2022). "We found that 8 out of 40 (20%) patients with lung cancer (PBMC) were cdc6 positive." (PMID 32249466, 2020). "To further study whether cdc6 can be used as a biomarker of circulating tumor cells, we detected cdc6 mRNA expression in PBMCs from lung cancer group and two control groups." (PMID 32249466, 2020).
lung carcinoma (continued). "Using this method, we studied whether cdc6 in Peripheral blood could be detected as a biomarker by examining cdc6 expression from PBMCs of patients with lung cancer." (PMID 32249466, 2020). "Importantly, lung cancer patients with higher CDC6 expression have the worse clinical outcome." (PMID 36257938, 2022). "Finally, we determined whether the CDC6 mRNA stability is indeed affected by the knockdown of either LCAT1 or IGF2BP2 in two lung cancer cell lines." (PMID 36257938, 2022). "However, the biological role of CDC6 in lung cancer remains to be further elucidated." (PMID 36257938, 2022). "To this end, we thoroughly characterized CDC6 as a new m6A target of the LCAT1/IGF2BP2 complex, which promotes CDC6 expression in lung cancer cells." (PMID 36257938, 2022). "Additionally, we found that Tmod3 was highly expressed in lung cancer cells and that knocking out Tmod3 enhanced the sensitivity of A549/PTX cells to paclitaxel, paralleling CDC6 depletion phenotypes." (PMID 41339304, 2025). "Susana Gonzalez and colleagues indicated that repression of the INK4/ARF locus could suppress the oncogenic activity of Cdc6 in lung cancer, which could inhibit the formation of multiprotein complexes, including ORC2, Cdc6, and MCMs." (PMID 36205357, 2023). "CDC6 is a downstream target of the LCAT1-IGF2BP2 axis and is upregulated in lung cancer tissues." (PMID 36257938, 2022). "The CDC6, CDC20, and CHEK1 genes are closely related to the occurrence and development of small-cell lung cancer, and CHEK1 is treated as a therapeutic target for lung cancer." (PMID 35632527, 2022). "Of all the 8 cdc6‐positive lung cancer samples, six were from small‐cell lung cancer and adenocarcinoma patients, and two were from patients with lung cancer whose tissue classification reports were not available." (PMID 32249466, 2020).
pancreatic cancer (19 papers, 2019 to 2026). "Then, we detected the clinicopathological correlation of 3 genes, we found that CDC6 and COL17A were associated with higher T classification, and CDC6 was associated with higher grade of pancreatic cancer." (PMID 39376555, 2024). "The scatterplots showed that, as the expression of COL17A1/GBP4/CDC6 increased and the risk score increased, the survival time of each pancreatic cancer patient decreased and the proportion of death increased." (PMID 39376555, 2024). "Cell division cycle 6 (CDC6) is thought to be significantly associated with pancreatic cancer and colorectal cancer (CRC)." (PMID 33564675, 2021). "In pancreatic cancer, CDC6 interacts with pathways affected by major mutations, like KRAS." (PMID 39052109, 2024). "Overexpression of CDC6 significantly promoted glycolysis and tumor progression in pancreatic cancer, whereas these pro-tumor effects were markedly abrogated by THBS1 knockdown." (PMID 42014675, 2026). "Functional experiments demonstrated that CDC6 promotes the proliferation, migration, and invasion of pancreatic cancer cells." (PMID 42014675, 2026). "Our results revealed that CDC6 expression is upregulated in pancreatic cancer, and its elevated expression is significantly correlated with unfavorable patient prognosis." (PMID 42014675, 2026). "Similar rescue experiments demonstrated that PVT1 can also promote the proliferation and migration of pancreatic cancer cells through CDC6, further confirming that CDC6 is a crucial downstream element in the PVT1-MYC duet’s facilitation of pancreatic cancer." (PMID 39376555, 2024). "Previous studies have shown CDC6 as dysregulated in many cancers, such as pancreatic cancer, mantle cell lymphoma, and hepatocellular carcinoma." (PMID 36257938, 2022). "The involvement of these targets of E2F7, such as BRCA1, CDC25A, CDC6 in pancreatic cancer deserves further investigation." (PMID 35201478, 2021). "As detailed studies on Cdc6 and pancreatic cancer are few and far between, here we discussed the potential involvement of Cdc6 via the downstream pathways of common genetic alterations in pancreatic cancer." (PMID 32010971, 2020). "In this review, we summarise the evidence for the role of Cdc6 overexpression in cancer, specifically that of pancreatic cancer." (PMID 32010971, 2020). "Given the potential of Cdc6 participation in pancreatic cancer, this review seeks to recapitulate and provide a brief overview of Cdc6 and its oncogenic potential, emphasising particularly its participation as part of a wider senescence network." (PMID 32010971, 2020). "The expression of CCNA2, CCNB1, CDC6 and GAPDH have all been implicated in various cancers, including lung, ovarian and pancreatic cancer." (PMID 32899298, 2020). "More importantly, we recapitulate the role of Cdc6 as part of the DNA damage response and on senescence—an important antitumour barrier—in the context of pancreatic cancer." (PMID 32010971, 2020). "Cancer and particularly pancreatic cancer remain a deadly disease with a dismal survival rate, beckoning a race toward improved detection and therapeutic targets of which Cdc6 shows potential." (PMID 32010971, 2020). "Collectively, our findings demonstrate that CDC6/THBS1/AKT signaling drives glycolysis and accelerates pancreatic cancer progression, suggesting that the CDC6/THBS1/AKT axis may serve as a promising therapeutic target for pancreatic cancer." (PMID 42014675, 2026). "This study aimed to examine the effects of Cdc6 on pancreatic cancer (PC) cells." (PMID 33020506, 2020). "Moreover, since CDC6 consistently yielded positive results in previous proliferation and migration assays, it suggests that CDC6 is a key downstream factor in the promotion of pancreatic cancer progression by the PVT1-MYC duet." (PMID 39376555, 2024).
pancreatic cancer (continued). "While the Cell Division Cycle 6 (CDC6) protein has been extensively characterized across multiple cancer types, its functional role in the pathogenesis of pancreatic cancer remains poorly understood." (PMID 42014675, 2026). "Eight genes (BUB1, BUB1B, CCNA2, CCNB2, CDC6, CDC20, CDK1, and TTK) among 21 common network genes were correlated with worse survival of pancreatic cancer, highlighted with P-value significantly <0.05." (PMID 32117719, 2020). "Interesting, we found six genes E2F7, CDC6, MMP14, PLK1, VASP and PKM2 were significantly correlated with the prognosis of patients with pancreatic cancer in TCGA, GSE71729, GSE78229 and GSE79668 datasets." (PMID 32950968, 2020). "Finally, CDC6 emerged as the most promising target within FSS, as determined through analysis of 17 CRISPR/Cas9 cohorts, and its efficacy in pancreatic cancer (PC) was validated through experimental investigation." (PMID 39739618, 2025). "Collectively, these findings underscore the critical role of CDC6 in modulating the immune landscape within the TME and suggest that its suppression may potentiate immunotherapeutic efficacy in pancreatic cancer." (PMID 39739618, 2025). "Therefore, we subsequently focused on exploring the functions and mechanisms of PVT1, CDC6 and COL17A1 in pancreatic cancer." (PMID 39376555, 2024).
hepatocellular carcinoma (15 papers, 2016 to 2026). A malignant tumor that arises from hepatocytes. "It has been reported that ZNF143-mediated H3K9 trimethylation upregulated CDC6 in hepatocellular carcinoma." (PMID 35109781, 2022). "But how CDC6 influenced tumor-infiltrating immune cells in hepatocellular carcinoma should be further explored." (PMID 33173413, 2020). "CDC6 dysregulation has a role in developing many cancers, like hepatocellular carcinoma." (PMID 35322101, 2022). "CDC6, cell division cycle 6, whose expression was promoted by zinc finger protein 143 (ZNF143) and accelerated hepatocellular carcinoma cell-cycle progression." (PMID 34566519, 2021). "The expression of CDC6 has a positive correlation with the tumor purity and the infiltration level range of B cells, CD8+T cells, CD4+T cells, macrophages, neutrophils, and dendritic cells in hepatocellular carcinoma (HCC) tissues." (PMID 39684684, 2024). "However, a pair of studies showed that miR-128-3p inhibits hepatocellular carcinoma (HCC) cell proliferation by binding to PIK3R1 and CDC6." (PMID 37700222, 2023). "Importantly, it has recently been shown that in highly aggressive hepatocellular carcinoma (HCC), miR-215-5p targets the 3’UTR of mRNA encoding Cell Division Cycle 6 (CDC6), which is involved in the assembly of the pre-replicative complex during the G1 phase of the cell cycle." (PMID 35922756, 2022). "Our results suggested CDC6 expression had strong correlations with tumor purity, infiltrating levels of CD8+ T cells, CD4+ T cells, macrophages, neutrophils and dendritic cells in hepatocellular carcinoma tissues." (PMID 33173413, 2020).